LINC00662 (long independently transcribed non-coding RNA 662)
Diseases named in the same sentence as LINC00662 in open-access papers (continued):
Sharing a sentence is not in itself a finding about the gene and the disease.
tumor (25 papers, 2017 to 2025). "The findings suggested that high expression of Linc00662 was linked to larger tumors (P = 0.006), later FIGO stage (P = 0.015), poorer tumor differentiation (P = 0.046), stromal infiltration (P = 0.002) and lymph node metastasis (P = 0.029)." (PMID 40764609, 2025). "High Linc00662 expression was strongly linked to increased tumor size, later FIGO staging, poorer tumor differentiation, mesenchymal infiltration, and lymph node metastasis, and high Linc00662 expression predicted a poor prognosis." (PMID 40764609, 2025). "Another lncRNA indicated as an oncogene in OS is LINC00662; it was found upregulated in OS tissues and cells, and correlated with poor prognosis; through its ceRNA activity, LINC00662 is able to promote cell proliferation, migration, invasion and tumor growth." (PMID 38835012, 2024). "We further studied LINC00662 using animal models, in vivo assays were conducted in a xenograft tumor model." (PMID 38169586, 2024). "LINC00662 has been reported in many different tumor types and is generally considered to be an oncogene." (PMID 38169586, 2024). "Recently, functional assays of LINC00662 in many cancers have been performed, and the results have indicated that LINC00662 knockdown acts as a tumor suppressor." (PMID 35123530, 2022). "The overexpression of LINC00662 significantly enhanced the tumor growth of A549 cells in vivo, as demonstrated by the tumor size, tumor volume, and tumor weight." (PMID 33589572, 2021). "LINC00662 has also been reported to facilitate a variety of cellular events, such as tumor-cell proliferation, invasion, and migration, and its expression has been correlated to clinicopathological characteristics in patients with tumors." (PMID 34354995, 2021). "High expression of LINC00662 was positively correlated with poor differentiation, large tumor size, and microvascular invasion." (PMID 31785055, 2020). "Tumor formation experiment in nude mice further confirmed that LINC00662 significantly regulated tumor growth and metastasis." (PMID 31900207, 2020). "In vivo xenograft studies in nude mice manifested that LINC00662 overexpression prominently accelerate tumor growth." (PMID 31900207, 2020). "To assess the role of LINC00662 in tumor development in vivo, sh-LINC00662 was transfected into U87 cells and xenografted into nude mice, and we found that LINC00662 suppression slows tumor growth in vivo." (PMID 32913464, 2020). "In addition, at the end of experiment, the average tumor weight of the LINC00662 knockdown group was significantly lower than that of the control group." (PMID 35371316, 2022). "Collectively, LINC00662 downregulation inhibits tumor angiogenesis." (PMID 35433661, 2022). "LINC00662 have revealed its oncogenic property in many tumor types 19-21, 33, however, the reason for how LINC00662 activated in tumorigenesis remain unclear." (PMID 35371316, 2022). "Thus, the relationship between LINC00662 and RNF144B was established through demonstrating their miR-16-5p interactions, and further studies also showed that the stable knockdown of LINC00662 inhibited tumor growth in vivo." (PMID 34354995, 2021). "Together these suggest that exosomal LINC00662 contributes to the tumor growth of NSCLC in vivo." (PMID 33589572, 2021). "Furthermore, Linc00662 promotes tumor growth, which was abolished by miR-15b-5p mimics." (PMID 38911389, 2024). "Therefore, LINC00662 significantly promotes HCC tumor growth and metastasis in vivo." (PMID 31785055, 2020). "Finally, LINC00662 promotes HCC tumor growth and metastasis via upregulating WNT3A." (PMID 31785055, 2020). "In summary, Linc00662 acts as an oncogene that promotes stemness of HSCC cells and facilitates xenograft tumor growth by binding to miR-15b-5p." (PMID 38911389, 2024). "It has been demonstrated that LINC00662 is up‐regulated in HCC and promotes HCC progression through both tumour cell‐ and macrophage‐dependent modes." (PMID 34907642, 2022).
tumor (continued). "Through inducing WNT3A secretion, LINC00662 activated Wnt/β‐catenin signaling in HCC cells in an autocrine manner and further promoted HCC cell proliferation, cell cycle, and tumor cell invasion, while repressing HCC cell apoptosis." (PMID 31785055, 2020). "Although we found that Linc00662 expression was not correlated with tumor stage or relapse-free survival in patients with HNSC, patients with high Linc00662 expression survived shorter than those with low Linc00662 expression." (PMID 38911389, 2024). "LINC00662 activates the Wnt/β-catenin signaling pathway in HCC cells in an autocrine manner by inducing WNT3A secretion, further promoting HCC cell proliferation, cell cycle, and tumor cell invasion, while inhibiting HCC cell apoptosis." (PMID 37056336, 2023). "Besides, tumor tissues of LINC00662 overexpression group had more positive expression of MMP-2 than vector group, whereas, tumor tissues of LINC00662 inhibition group had lower positive expression of MMP-2 than siNC group." (PMID 31900207, 2020). "However, the role and function of Linc00662 and miR-15b-5p in HSCC and their effects on tumor cell stemness have not been completely elucidated." (PMID 38911389, 2024).
cancer (23 papers, 2020 to 2025). A tumor composed of atypical neoplastic, often pleomorphic cells that invade other tissues. "This study aimed to investigate the effect of Linc00662 on cancer stemness and the underlying mechanism by which Linc00662 regulates cancer stemness in HSCC by sponging miR-15b-5p." (PMID 38911389, 2024). "In the present work, we have summarized the latest evidence concerning the abnormal expression of LINC00662, its associated clinical features, and molecular mechanisms, and we discuss both its prognostic and therapeutic values for malignant tumors." (PMID 34354995, 2021). "Based on the recent studies, the overexpression of LINC00662 was significantly linked to poor prognosis in different cancer types." (PMID 34354995, 2021). "The results suggested that overexpression of Linc00662 promotes pheroidization of FaDu cells, but transfection with miR-15b-5p mimics significantly reversed the Linc00662-mediated promoting effect of cancer cell stemness." (PMID 38911389, 2024). "LINC00662 is shown to promote the development and progression of cancer and have relationships with a wide range of tumors in various systems, such as the reproductive, respiratory, and nervous systems." (PMID 35893039, 2022). "Overall, these data suggest a tumor-promotive role of linc00662 in cancer, while simultaneously being secreted into the TME through exosomes, which promotes macrophages towards a M2 phenotype." (PMID 34439281, 2021). "LncRNA LINC00662 has also been reported to be a key regulator of biological behaviors in many cancers." (PMID 34621314, 2021). "In human lung carcinoma, elevated levels of linc00662 were detected in cancer cells and as well as plasma exosomes of NSCLC patients and have been correlated with poor survival." (PMID 34439281, 2021). "LINC00662 has been shown to be upregulated in malignant tumors and has been confirmed to promote the development of malignant tumors." (PMID 34354995, 2021). "In terms of the molecular mechanisms by which LINC00662 acts in cancers, studies have increasingly shown that LINC00662 mainly participates by regulating target miRNA by acting as a ceRNA." (PMID 34354995, 2021). "Regarding the up-regulated lncRNAs, only a low number of them have been previously implicated in cancer, such as the up-regulated CASC15, LINC00662, LINC01272, LINC00857, LINC00092, LINC00673 and the down-regulated LINC00657, LINC01087 and LINC00993." (PMID 32753692, 2020). "The various functional mechanisms and oncogenic roles of LINC00662 further suggest the extensive involvements of LINC00662 in many aspects of cancers." (PMID 31785055, 2020). "LINC00662 is upregulated in a variety of malignant tumors, and the upregulated expression of LINC00662 is also closely related to the poor prognosis, radioresistance and chemoresistance of cancer patients." (PMID 35692795, 2022). "LINC00662 exhibits a carcinogenic role in multiple types of human cancers." (PMID 35037833, 2022). "LINC00662 was proved to serve as an oncogene in several cancers." (PMID 35551606, 2022). "Moreover, LINC00662 has been reported to function as a competing endogenous RNA (ceRNA) by sponging miRNAs in cancers." (PMID 34621314, 2021). "Since the oncogenic effect of LINC00662 has been well clarified in other cancers, we hypothesized that LINC00662 might play a role in OS." (PMID 34621314, 2021). "Therefore, LINC00662, which is a potential biomarker for early prediction of cancer initiation, is a novel promising target for cancer." (PMID 34354995, 2021). "In terms of mechanisms, LINC00662 regulates gene expression by interacting with both proteins and with RNAs, so it may be a potential biomarker for cancer diagnosis, prognosis, and treatment." (PMID 34354995, 2021). "The functions of LINC00662 were also investigated in human cancers." (PMID 32633082, 2020). "In addition, LINC00662 has been reported to serve as a ceRNA in some cancers." (PMID 34621314, 2021).
cancer (continued). "In addition, recent reports confirmed the prognostic role of LINC00662 in multiple types of cancer." (PMID 34148056, 2021). "In order to confirm that METTL3 and LINC00662 were related to the angiogenesis of CRC, 64 pairs of CRC and para-cancer tissues were collected in this study." (PMID 36114893, 2022). "Additionally, Linc00662 was highly expressed in fresh HSCC tissues (n = 17), in contrast to the corresponding para-carcinoma tissues." (PMID 38911389, 2024). "Upregulation of LINC00662 expression has been detected in many cancers when compared to adjacent non-cancerous tissues." (PMID 34354995, 2021). "However, other evidence indicates that HNRNPH1 can localize to the cytoplasm in cancer cells, suggesting the possibility of interaction between HNRNPH1 and LINC00662." (PMID 34148056, 2021). "However, a possible pan-cancer role for LINC00662 has not been clear, so a comprehensive review of its expression levels, biological functions, and clinical features is warranted." (PMID 34354995, 2021).
LINC00662 also shares sentences with these, for which no sentence is quoted: lymph node metastasis (3 papers); bladder carcinoma (1).